CDK4P1 (cyclin dependent kinase 4 pseudogene 1)
Synonyms: CDK4PS
Gene: Processed pseudogene on chromosome 1 (105,433,994 to 105,434,821, forward strand). Ensembl gene ENSG00000225036.
Diseases named in the same sentence as CDK4P1 in open-access papers:
CDK4P1 is named in the same sentence as 2 diseases in open-access papers, as found by Europe PMC text mining. Sharing a sentence is not in itself a finding about the gene and the disease.
CDK4P1 shares sentences with these, for which no sentence is quoted: angle-closure glaucoma (1 paper); cataract (1).